PKN2 (protein kinase N2)
Diseases named in the same sentence as PKN2 in open-access papers (continued):
Sharing a sentence is not in itself a finding about the gene and the disease.
tumor (continued). "Furthermore, we investigated the correlation between clinical parameters of ESCC patients and PKN2 expression in ESCC tumor tissues." (PMID 40069590, 2025). "Overexpression of PKN2 resulted in suppressed tumor growth compared to the control group." (PMID 40515512, 2025). "The inhibitory effect of PKN2 on angiogenesis was also confirmed in a mouse tumor model." (PMID 40515512, 2025). "Furthermore, VEGFA and bFGF levels were examined in the tumor tissues, showing a significant downregulation of both factors in PKN2 overexpressing tumors." (PMID 40515512, 2025). "PKN2 may regulate tumor growth and metastasis by influencing the activity of immune cells and the composition of the tumor microenvironment." (PMID 40069590, 2025). "Furthermore, we examined the correlation between PKN2 expression in tumor tissues and the clinical characteristics of ESCC patients." (PMID 40069590, 2025). "This study concentrated on the regulation of tumor-infiltrating PMN-MDSCs by PKN2 and corroborated the elevated expression of PKN2 in MDSCs, particularly PMN-MDSCs, through the utilization of the GEO database, clinical specimens from ESCC patients, and artificially induced EC mouse models." (PMID 40069590, 2025). "Furthermore, the expression of PKN2 was examined in ten paired clinical samples, including PBMCs and tumor tissues." (PMID 40069590, 2025). "One thousand TB32048 (C57BL/6 background) cells were implanted into the pancreas to initiate syngeneic orthotopic tumor growth in both male and female littermate RosaCreERT+/WT: PKN2+/+ (WT), PKN2fl/+ (heterozygous [HET]), and PKN2fl/fl (KO) mice (C57BL/6 background)." (PMID 35081338, 2022). "The existent study of the function of PKN2 in tumor is relatively controversial." (PMID 34745257, 2021). "We also detected circ_SEPT9/miR‐1225/PKN2 axis in the tumour of nude mice." (PMID 33090705, 2020). "Additionally, we found that a higher PKN2 expression in the tumor tends to confer a significantly better prognosis." (PMID 29368606, 2018). "Interestingly, we observed that the overexpression of PKN2-WT led to the suppression of tumor growth while PKN2-K686R led to the accelerated tumor growth in vivo." (PMID 29368606, 2018). "PKN2 is required for cell cycle progression, cell migration, cell adhesion and transcription activation signaling processes and it plays important roles in tumor cell migration, invasion and apoptosis." (PMID 29368606, 2018). "Compared to the macrophages in WT group samples, the macrophages isolated from PKN2-WT tumor showed significantly higher expression of Il1b, Tnf, Cxcl9, Il23, Ros1 and Il12b and significantly lower expression of Tgfb1, Vegfa, Egf, Retnla and Il10, illustrating predominant M1 phenotype." (PMID 29368606, 2018). "PKN2 is required for tumor cell migration, invasion and apoptosis." (PMID 29368606, 2018). "Moreover, IHC staining showed that p-Erk1/2 was upregulated in PKN2-WT overexpressed murine tumor tissue." (PMID 29368606, 2018). "Studies suggest that PKN2 may play a pivotal role in tumor growth, invasion, and metastasis." (PMID 40515512, 2025). "The results demonstrated that, in comparison to PBMCs, PKN2 expression was elevated in myeloid cells, M-MDSCs, and polymorphonuclear myeloid derived suppressor cells (PMN-MDSCs) of tumor tissues." (PMID 40069590, 2025). "Our findings revealed a significant correlation between PKN2 expression in PMN-MDSCs of tumor tissues and tumor stage." (PMID 40069590, 2025). "The Protein Kinase N2 (PKN2) gene plays a role in the regulation of cell cycle progression, cell migration, actin cytoskeleton assembly, and tumor cell invasion." (PMID 35629146, 2022). "For example, PKN2 is a PKC-related serine/threonine-protein kinase and it is related to tumor cell migration, invasion and apoptosis." (PMID 34571875, 2021).
tumor (continued). "There were significantly more iNOS+/CD86+ cells in high PKN2 expression tumor tissues, while the number of CD206+/CD163+ cells was significantly higher in low PKN2 expression tumor tissues." (PMID 29368606, 2018). "While we present evidence that this results in CAF phenotypic switching in tumors, we cannot rule out the impact of PKN2 deletion on other cells in the tumor microenvironment (TME)." (PMID 35081338, 2022). "Importantly, SNTB1 promotes tumor growth and progression of CRC, possibly by reducing the expression of PKN2 and activating the ERK and AKT signaling pathway." (PMID 34663329, 2021). "PKN3 has been considered the primary player in PKN-dependent tumour cell invasion with no role for PKN1 or PKN2." (PMID 21754995, 2011). "The function of PKN2 in tumor angiogenesis has never been established." (PMID 40515512, 2025). "Koh H's research indicated that the C‐terminal region of PKN2 can interact with Akt, inhibit threonine phosphorylation at 308 and 473 site of Akt, and specifically downregulate the activity of Akt protein kinase, blocking the activity of AKT signaling pathway and promoting tumor cell apoptosis." (PMID 33090721, 2020). "However, in the intestine, the role of PKN2 in the regulation of tumor proliferation has never been reported, and the immunomodulatory effects of PKN2 have not been discussed." (PMID 29368606, 2018). "Additionally, there was a strong negative relation between PKN2 and p-Erk1/2 expression levels in murine tumor tissue." (PMID 29368606, 2018).
cancer (18 papers, 2015 to 2025). A tumor composed of atypical neoplastic, often pleomorphic cells that invade other tissues. "Previous studies have shown that PKN2 depletion impairs migration in both cancer and normal cells through its role in organizing actin filaments at the cell rear." (PMID 39843538, 2025). "ROCK‐targeting compounds used in these studies, including Y27632 and fasudil, also target the Rho‐effector kinase PKN2, which also regulates migration and invasion of mesenchymal cancer cells and fibroblasts." (PMID 35533046, 2022). "In spheroid co-cultures with PDAC cells, loss of PKN2 prevents PSC invasion but, counter-intuitively, promotes invasive cancer cell outgrowth." (PMID 35081338, 2022). "Protein kinase N2 (PKN2) is a PKC-associated serine/threonine-protein kinase and act as a chemical tool to explore several types of cancer." (PMID 34745257, 2021). "In this work we describe initial efforts in the development of a selective chemical tool for protein kinase N2 (PKN2), a relatively unexplored kinase of interest in several types of cancer." (PMID 32085971, 2020). "PKN2 is highly expressed in triple-negative breast cancer cells and is required to support the growth of cancer." (PMID 29368606, 2018). "Previous reports indicated that PKN2 was relatively highly expressed and had a significant role in the migration and invasion of cancer cells." (PMID 29069770, 2017). "To validate our observations in human cancer data, we defined a PKN2-null matrisome signature of statistically significant DE genes from PSCs, which concurred with expression in orthotopic tumors; we selected the top 11 genes as a high-confidence PKN2KO matrisome gene set." (PMID 35081338, 2022). "These previous studies have elucidated functions for PKN2 using molecular and cell biology techniques, and the conclusions would be greatly supported by validation through the use of small molecule inhibitors, especially to evaluate PKN2′s potential as a cancer drug target." (PMID 32085971, 2020). "Further, during development, neural crest cells fail to migrate in PKN2KO embryos, suggesting emerging dependence on PKN2 post-EMT, with implications for cancer cell invasion." (PMID 35081338, 2022). "Indeed, we recently contributed to work identifying that PKN2 and ROCK1 collaborate to mediate rear end retraction in durotaxis, focusing on mesenchymal migratory cancer cell models, a process which also requires mechanical activation of YAP." (PMID 35081338, 2022). "We reported a specific non-redundant role for PKN2 in cancer cell migration." (PMID 26774483, 2016).
infection (4 papers, 2012 to 2025). The state of being infected such as from the introduction of a foreign agent such as serum, vaccine, antigenic substance or organism. "We detected robust phosphorylation of kinases PKN1 and PKN2 upon infection with all variants." (PMID 39653747, 2024). "With increasing infection time, the expression levels of IKBKG and KRAS2 increased, whereas the expression levels of MAP3K7, MAP3K2, AKT1, CDC37, and PKN2 decreased." (PMID 40078537, 2025). "In 3D4/21 cells, with increasing NS5A infection time, the protein expression of AKT1, IKBKG, CDC37, MAP3K2, and PKN2 decreased, whereas the protein expression of KRAS2 and MAP3K7 increased." (PMID 40078537, 2025). "The results revealed that with increasing infection time, the expression of IKBKG, AKT1, CDC37, MAP3K2, and PKN2 decreased, whereas the expression of MAP3K7 and KRAS2 increased." (PMID 40078537, 2025).
PKN2 also shares sentences with these, for which no sentence is quoted: viral infections (2 papers); Alzheimer disease (1); atrial fibrillation (1); bacterial infection (1); ciliopathy (1); dementia (1); fibrosis (1); gastric cancer (1); heart disease (1); hypertrophy (1); Intellectual disability (1); leukemia (1); metastatic disease (1); nevus (1); osteosarcoma (1); Papillary Thyroid Carcinoma (1); polyp (1); prostate (1); prostate adenocarcinoma (1); prostate tumour (1); pulmonary fibrosis (1); R6 (1); rheumatoid arthritis (1); sarcoma (1); STAR syndrome (1); triple-negative breast carcinoma (1).